HMGB1 (high mobility group box 1)
Diseases named in the same sentence as HMGB1 in open-access papers (continued):
Sharing a sentence is not in itself a finding about the gene and the disease.
lung carcinoma (continued). "In conclusion, HMGB1 was released in human-derived lung cancer cells after X-ray irradiation and in human-derived neuroblastoma cells after 131I-MIBG administration, but HMGB1 was not released in normal human epidermal keratinocyte cells under the same conditions." (PMID 40583575, 2025). "Finally, we validated through both in vitro and in vivo experiments that knocking down the HMGB1 gene, one of the modeling genes of Necroptosis.Sig, in the A549 lung cancer cell line can suppress the malignant biological behavior of tumor cells." (PMID 39717781, 2024). "Therefore, to address the pleiotropic effect of glycyrrhizin, we decided to use siRNA to specifically decrease the levels of endogenous HMGB1 in lung cancer cells." (PMID 39100092, 2024). "In lung cancer patients, miR-325-3p and HMGB1 are underexpressed and overexpressed, respectively." (PMID 39759512, 2024). "In lung cancer cells, HMGB1 levels were increased with combined ATR inhibition and ablative radiotherapy compared to radiotherapy alone, suggesting a potential synergistic effect between ATR inhibition and radiotherapy in boosting HMGB1-mediated immunogenicity." (PMID 39487895, 2024). "Knockdown with siRNA led to a significant decrease in total HMGB1 protein in lung cancer cells." (PMID 39100092, 2024). "Based on this, we investigated the relationship between HMGB1 and lipid metabolism in lung cancer." (PMID 39100092, 2024). "In lung cancer tissues, HMGB1 was positively correlated with circHERC1." (PMID 37932766, 2023). "Moreover, a retrospective analysis performed using GEPTA data base showed a dependence of overall and disease-free survival on HMGB1 level in patients with lung cancer." (PMID 37880798, 2023). "Another study revealed that high HMGB1 may induce tumorigenesis, metastasis and chemotherapy resistance in lung cancer." (PMID 37143472, 2023). "Similarly, following several cycles of chemotherapy plus radiotherapy, lung cancer patients with high serum HMGB1 levels have shorter overall survival." (PMID 36831371, 2023). "These in vivo findings in ectopic xenograft mouse models were consistent with the in vitro observations, and hence support that overexpression of circHERC1 can promote in vivo tumorigenicity of lung cancer cells via the miR-142-3p-HMGB1 axis and interaction with FOXO1." (PMID 37932766, 2023). "Overall, for the first time, our data demonstrated that circHERC1 plays an oncogenic role in lung cancer development via miR-142-3p/HMGB1 axis which enhanced the expression of HMGB1 to activate the MAPK/ERK and NF-κB pathways by sponging miR-142-3p in cancer cells." (PMID 37932766, 2023). "qRT‒PCR and western blot analysis showed that HMGB1 expression at both the mRNA and protein levels was significantly reduced in lung cancer cells transfected with miR-142-3p mimics, while HMGB1 expression was increased in cells transfected with miR-142-3p inhibitor." (PMID 37932766, 2023). "After CRT exposure, dead lung cancer cells will secrete HMGB1, which has a dual effect depending on whether it is extracellular or intracellular." (PMID 36619616, 2022). "High expression of HMGB1 was found in lung cancer tissues, and its release upon pyroptotic cell destruction could be used as a prognostic marker of survival." (PMID 36267972, 2022). "Also, TCGA-based analysis revealed an inverse correlation between HMGB1 level and outcome of lung cancer." (PMID 36542153, 2022). "We found that CAFs of lung cancer possess a high basal level of autophagy compared to NFs, and CAFs autophagy activity facilitates the promoting effect of CAFs on lung cancer metastasis via secreting HMGB1." (PMID 34552063, 2021). "The role of CAF-secreted HMGB1 in lung cancer cell migration was assessed by wound healing assay." (PMID 34552063, 2021). "Finally, the circRNA circ_0007385 enhanced cell proliferation, migration, invasion, and chemoresistance in lung cancer through upregulating miR-519d-3p and thus downregulating HMGB1." (PMID 34073766, 2021).
lung carcinoma (continued). "No blood markers for predicting postoperative AE-ILD caused by lung resection have been reported; therefore, this study showed that HMGB1 can be a promising biomarker for predicting postoperative AE-ILD in patients with lung cancer and ILD, especially in those treated with lobectomy." (PMID 33980944, 2021). "As we have demonstrated that the autophagy activity contributes to CAFs’ effect on the activation of TLR4/NF-κB pathway in lung cancer cells, we further investigated whether HMGB1 is involved in this event." (PMID 34552063, 2021). "Our data showed that HMGB1 significantly increased lung cancer cell migration and motility." (PMID 33807275, 2021). "In this study, we investigated the role of HMGB1 in phenotype transitions in lung cancer cells." (PMID 33807275, 2021). "In lung cancer, no associated literature has investigated the association between HMGB1 and DRP1 until now." (PMID 33807275, 2021). "Therefore, in this study, we aimed to evaluate the mechanism by which HMGB1 regulates motility and migration during lung cancer metastasis." (PMID 33807275, 2021). "Taken together, these findings indicate that HMGB1 might play a critical role in the regulation of membrane tension, dynamics, and polarization in lung cancer cells." (PMID 33807275, 2021). "Likewise, the lncRNA UCA1 exerted pro-tumoral activity in lung cancer, acting mechanistically by upregulating HMGB1 expression through miR-193a-3p inhibition." (PMID 34073766, 2021). "Moreover, the results of lung cancer xenograft animal model confirmed that the overexpression of HMGB1 promotes tumor growth and increases DRP1 expression and phosphorylation in the nucleus and cytoplasm." (PMID 33807275, 2021). "In summary, we demonstrated the significant role of HMGB1 in regulating lung cancer migration." (PMID 33807275, 2021). "Genotypes of REV3L rs462779 and HMGB1 rs1045411 may be biomarkers for predicting platinum-based chemotherapy prognosis in lung cancer patients." (PMID 32489453, 2020). "After CRT exposure, late dying cells secret HMGB1, which has a dual role in lung cancer depending on whether it is intracellular or extracellular." (PMID 32456685, 2020). "Indeed, miRNA-218 and miRNA-1284 have been described for suppressing HMGB1 in lung cancer and osteosarcoma models, respectively." (PMID 32983090, 2020). "In this study, we investigate the associations of HMGB1 (rs1045411, rs1412125, and rs2249825), REV3L (rs462779 and rs465646) and NFE2L2 (rs6706649, rs6721961, and rs35652124) with platinum-based chemotherapy prognosis in lung cancer patients." (PMID 32489453, 2020). "The REV3L rs462779 and HMGB1 rs1045411 may serve as prognosis markers in lung cancer patients with platinum-based chemotherapy." (PMID 32489453, 2020). "Moreover, HMGB1 levels in the sera of lung cancer patients were increased after DOC combined with L-OHP treatment." (PMID 30744691, 2019). "Recently P38-GSK3β-Snail signaling pathway induces EndoMT via HMGB1; however, the role of Snai1 in lung cancer angiogensis is largely unknown." (PMID 30975732, 2019). "Drugs designed for regulating the level of HMGB1 may have a potential clinical value for lung cancer patients." (PMID 29568761, 2018). "However, p65 siRNA treatment significantly reduced MMP2 expression, suggesting that HMGB1 accelerated the MMP2 expression via the NF-κB pathway to promote lung cancer migration and invasion." (PMID 29850505, 2018). "HMGB1 can promote the migration and invasion of lung cancer cells." (PMID 29568761, 2018). "High serum level of HMGB1 can be a potential clinical biomarker for lung cancer." (PMID 29568761, 2018). "In order to investigate whether the high expression of HMGB1 was correlated with the poor prognosis of patients with lung cancers, we analyzed the 5-year survival rates of 90 cases of lung cancer patients using Kaplan–Meier survival curves." (PMID 29850505, 2018). "Xiao and Liu suggested that silencing of HMGB1 inhibited lung cancer migration and invasion." (PMID 29850505, 2018).
lung carcinoma (continued). "In addition, p65 siRNA was transfected into the A549 and H1299 lung cancer cell lines, together with HMGB1 treatment." (PMID 29850505, 2018). "HMGB1 is one of the most abundant chromatin-binding proteins and has been shown to play oncogenic roles in tumorigenesis of different tumor types including lung cancer." (PMID 30134604, 2018). "In order to determine whether HMGB1 promoted lung cancer cell invasion, the lung cancer cell lines, A549 and H1299, were pretreated with HMGB1, and the Transwell assay was used to determine the changes of cell invasion." (PMID 29850505, 2018). "Taken together, these data suggested that HMGB1 may be a potential prognosis and therapeutic marker for lung cancer." (PMID 29850505, 2018). "Similarly, HMGB1 can promote the migration and invasion of lung cancer cells and regulate the metastasis of lung cancer." (PMID 29568761, 2018). "Further studies of HMGB1-regulated signalling pathways implicated in lung cancer EMT and cancer progression are required to validate the potential of miR-200c for use in therapy for lung cancer." (PMID 28727734, 2017). "Other reasons might involve the secretion of HMGB1 from apoptotic or necrotic cells from the core region in lung cancer tissues." (PMID 26840258, 2016). "In summary, we found that HMGB1 levels were elevated in NSCLC tissues over those of healthy non-cancer control tissues and were closely related to histologic types and TNM stage; however, HMGB1 only affected the survival time of lung cancer subclass (ADC) patients." (PMID 26840258, 2016). "However, in other cell types such as neuroblastoma and H1299 lung cancer cells, acidosis stimulates the expression of oncogenes such as c-Myc and high mobility group box 1 (HMGB-1)." (PMID 25988385, 2015). "In contrast, 10 Gy significantly reduced growth in all cell lines (P ≤ 0.005) without significantly reducing viability, yet also induced significant ATP release in lung cancer cells (P = 0.0002) and HMGB1 secretion in lung (P = 0.0003) and prostate (P = 0.0007) cancer cells." (PMID 24480782, 2014). "Interestingly, factors diffusing from stromal fibroblasts have recently been shown to up-regulate intracellular HMGB1 in lung cancer cells." (PMID 25512109, 2014). "For example, in lung cancer, the expression of HMGB1 and RAGE are reduced." (PMID 19476625, 2009). "Interestingly, monounsaturated fatty acid (MUFA) availability affected the expression of programmed death ligand-1 (PD-L1), a pivotal immune checkpoint target in lung cancer cells and immune cells, as well as HMGB1, suggesting a novel approach to modulating the immune response." (PMID 39100092, 2024). "The effects of B. juncea or mustard and its constituents on lung cancer treatment are shown via increasing antioxidant activities and antiproliferation activity markers, apoptosis and improving levels of immunoglobulins, Cas, HMGB1, LDH and pro‐inflammatory cytokines." (PMID 37697969, 2023). "Gathering the information obtained from cell lines with respect to HMGB1 release and translating this information to the tumor suggest that, in lung cancer patients, tumors consisting of a vast proportion of CDDP-susceptible cells may release HMGB1 as a consequence of cell death." (PMID 34966671, 2021). "Notably, both CAFs and NFs release more HMGB1 than lung cancer H661 and A549 cells." (PMID 34552063, 2021). "Taken together, our studies showed that the high expression of HMGB1 in lung cancer, which may be used in the prognoses of lung cancer patients, promoted lung cancer invasion and metastasis by upregulating the expression and activity of MMP-2 via an NF-κB-dependent pathway." (PMID 29850505, 2018). "However, whether the anticancer effect of glycyrrhizin in lung cancer relies on downregulating the expression of HMGB1 is unclear." (PMID 29568761, 2018). "However, whether the anti-lung cancer effect of glycyrrhizin involves suppression of HMGB1 remains unknown." (PMID 29568761, 2018).
lung carcinoma (continued). "Artesunate and dihydroartemisinin may exert immunomodulatory effects by regulating HMGB1 expression, inhibiting TLR4/NF-κB activation, decreasing TNF-α, IL-6, IL-1β, iNOS, and Cox-2 expression, and attenuating inflammation caused by pneumonia, lung injury, lung fibrosis, and lung cancer." (PMID 41347152, 2025). "In radiotherapy, HMGB1 both activates anti-tumor immunity and aids DNA repair, interacting with Ku70 in nasopharyngeal carcinoma and modulating the TLR4/NF-κB axis in lung cancer." (PMID 40969278, 2025). "Paclitaxel is an ICD inducer whose activity is characterized by the release of HMGB1 in osteosarcoma cells and upregulation of CALR in lung cancer cells." (PMID 39759512, 2024). "Using multiple lung cancer cell lines (A549, HCC827, H1299, and H23), we measured the level of intracellular HMGB1 following our delipidation procedure." (PMID 39100092, 2024). "Studies have confirmed that high mobility group box 1 (HMGB1) promotes the expression of phosphorylated DRP1, increasing mitochondrial fission in lung cancer cells and promoting metastasis." (PMID 39430236, 2024). "Although the fluorescent modification increased molecular weight of HMGB1, we confirmed that HMGB1-GFP behaved similarly to what we had observed of endogenous HMGB1 in lung cancer cells." (PMID 39100092, 2024). "Compared with X-rays, carbon ions increased the exposure of high mobility group box 1 (HMGB1) while relatively reduced the exposure levels of immunosuppressive factors IL-10 and TGF-β in lung cancer cell lines." (PMID 36348363, 2022). "In this study, we examined the role of HMGB1 in lung cancer cell lines and its biological importance during exposure to CDDP, which is the principal drug used in the treatment of lung cancer patients." (PMID 34966671, 2021). "Collectively, HMGB1 plays a key role in the formation of lamellipodia and filopodia by regulating cytoskeleton dynamics and DRP1 expression to promote lung cancer migration." (PMID 33807275, 2021). "Further investigations are needed to elucidate the utility of serum HMGB1 as a predictive biomarker and molecular target for preventing triggered AE, including postoperative AE-ILD, in patients with lung cancer and ILD." (PMID 33980944, 2021). "Increased HMGB1 and CXCL11 expressions were positively correlated with prolonged overall survival of lung cancer patients." (PMID 30744691, 2019). "Tumor infiltrated CD8+ T cells are increased in lung cancer patients after DOC therapy, identifying the activation of apoptosis and the release of HMGB1 and CXCL11 as key events underpinning lung carcinoma cells-elicited leukocyte attraction." (PMID 30744691, 2019). "In the presence of HMGB1, DC receptors CXCR3 and CCR5 are upregulated in the tumor microenvironment of lung cancer tissue, enhancing migration of DCs." (PMID 31379812, 2019). "The matrix metalloproteinase-2 (MMP-2) expression and activity were upregulated after treatment with HMGB1, while the upregulated expression of MMP-2 stimulated by HMGB1 in lung cancer cells was significantly reduced with the blockage of si-p65." (PMID 29850505, 2018). "Results of this current study suggested that polymorphisms in HMGB1 showed an association with the risk of lung cancer in non-smokers and female population and it could be used as a biomarker for the risk of lung cancer, especially for the risk of LAD and SCLC." (PMID 29617336, 2018). "However, it remains unknown whether miR-200c can inhibit HMGB1 expression in lung cancer cells." (PMID 28727734, 2017). "By contrast, HMGB1/RAGE interaction was reported to diminish tumor cell migration in vitro and lead to decreased metastasis in a lung cancer model." (PMID 26854151, 2015). "Our study showed that knockdown of HMGB1 decreased LC3-II levels and inhibited autophagy activity, resulting in increased apoptosis, which is the same result found in non–small cell lung cancer." (PMID 26702616, 2015).
lung carcinoma (continued). "In another recent study that has reported elevated plasma HMGB1 levels in patients with mild to moderate COPD, 82% of the COPD patients had comorbid lung cancer." (PMID 24758342, 2014). "In lung cancer cells treated with IFNG, both transcription and secretion of HMGB1 are increased." (PMID 39945555, 2025). "HMGB1, S100A9, and HSP90 were shown to be predictive and prognostic markers for distinguishing cancer patients from healthy controls in several cancer types such as mesothelioma, colorectal, gastric, and lung cancers." (PMID 39768997, 2024). "Etop was previously found to increase extracellular ATP and HMGB1 when used in combination with cisplatin, but not as a single agent, in a lung cancer cell line." (PMID 39682260, 2024). "In addition to IL6, the promoting effect of CAFs on EMT programming in lung cancer cells is also mediated by the secretion of CXCL12 and high mobility group box 1 (HMGB1), which activate the CXCR4/β-catenin/PPARδ and NFκB signaling pathways, respectively." (PMID 38139154, 2023). "To determine if WFA can induce ICD in lung cancer, we treated LLC, H1650 and A549 cells with WFA and then collected the cells or supernatants to measure the levels of cell surface expressed CRT (ecto-CRT) or secreted HMGB-1, respectively." (PMID 37370701, 2023). "In addition, Afzelin activated endoplasmic reticulum (ER) stress and increased ATP, HMGB1, and CRT levels in lung cancer cells, indicating that Afzelin induced immunogenic cell death (ICD)." (PMID 37891619, 2023). "The qPCR analysis consistently demonstrated that HMGB1 was abundantly expressed at tumor tissues but not adjacent areas in samples of lung cancers." (PMID 36542153, 2022). "For example, Coxsackievirus B3 (CVB3) mediated cytotoxicity in lung cancer cells with high CRT exposure, HMGB1 release, and ATP secretion, whereas CVA21 mediated cytotoxicity in bladder cancer cells positively correlated with high CRT exposure and HMGB1 release but not ATP release." (PMID 36755812, 2022). "Similarly, Adenovirus (Ad), Semliki Forest virus (SFV4), and Vaccinia virus (VACV) mediated CRT exposure, the release of HMGB1 and HSP90, as well as ATP release in lung cancer and bone cancer cells." (PMID 36755812, 2022). "Besides, in the treatment of lung cancer, CRT plays a similar role as HMGB1 so that it can be used to assess the extent of ICD induced by the treatment." (PMID 36619616, 2022). "In addition, HMGB1 and DRP1 expressions were positively correlated and exhibited poor prognosis and survival in patients with lung cancer." (PMID 33807275, 2021). "Interestingly, in lung cancer, RSF1-IT2 functions as a ceRNA to sponge miR-129-5p targeting SNAI1 and HMGB1, facilitating tumor metastasis and invasion." (PMID 34926441, 2021). "However, the correlation between HMGB1 and DRP1 in lung cancer and the way that HMGB1 drives mitochondrial fission to control cell migration and mobility have not been explored." (PMID 33807275, 2021). "The lncRNA PCA3 downregulated the expression of miR-218-5p, whose negative targeting of HMGB1 was evaluated in endometrial carcinoma, lung cancer, and prostate cancer, leading to a decrease in tumor proliferation, migration, invasion, and chemoresistance." (PMID 34073766, 2021). "Similarly, in the cytoplasm of lung cancer, EP suppressed the growth, invasion and migration and induced apoptosis of NSCLC cells via the HMGB1/RAGE axis and the NF-κB/STAT3 pathway." (PMID 32742812, 2020). "In our study, we did not compare HMGB1 expression in samples of lung cancer patients and benign tumor patients, making it impossible to assess the application of HMGB1 as a diagnostic marker." (PMID 30744691, 2019). "Furthermore, varying expression patterns of HMGB1 have been observed in patients with asthma, COPD, endometrial carcinoma, bladder cancer, and lung cancer, and the pathogenesis of all has been considered to be importantly related to EMT 42-44." (PMID 31839751, 2019).